HDAC2 (histone deacetylase 2)
Diseases named in the same sentence as HDAC2 in open-access papers (continued):
Sharing a sentence is not in itself a finding about the gene and the disease.
gastric cancer (28 papers, 2008 to 2025). A primary or metastatic malignant neoplasm involving the stomach. "In some cancers, such as colon, endometrial, and gastric cancers, a truncating HDAC2 mutation has been found." (PMID 27886118, 2016). "High levels of expression of class I HDACs, especially HDAC2, are clinically associated with nodal spread and prognosis of gastric cancer patients." (PMID 21080974, 2010). "HDAC2 expression was found to be abnormal in cancer cells, and HDAC2 inhibitors suppressed cell motility, invasion, and proliferation, as well as causing cell death, in gastric cancer cells." (PMID 36034650, 2022). "For example, research has indicated that inhibiting histone deacetylase 2 (HDAC2) can lead to increased E-cadherin expression, thereby reducing metastasis in gastric carcinoma." (PMID 40585607, 2025). "HDAC2 also affects the proliferation of gastric cancer cells by regulating cell cyclins and plays a role in Myc-mediated tumorigenesis." (PMID 35941558, 2022). "HDAC-2 overexpression has also been associated with advanced disease stage in thyroid, NSCLC and gastric cancer." (PMID 33799478, 2021). "Aberrant expression of HDAC2 was reported in cancer cells, and treatment with HDAC2 inhibitors reduced cell motility, cell invasion, and cell growth, and induced cell death in gastric cancer cells." (PMID 32210140, 2020). "Downregulation of HDAC2 suppressed gastric cancer proliferation, whose expression is upregulated and inversely associated with miR-31 levels." (PMID 29333444, 2017). "Overexpression of HDAC2 has been observed in uterine, cervical, and gastric cancers, while HDAC2 overexpression was detected in ovarian cancer and Hodgkin’s lymphoma." (PMID 27886118, 2016). "On western blotting analysis, OCUM-2MD3 cells showed high levels of HDAC1 and HDAC2 compared with the other human gastric cancer cell lines." (PMID 21080974, 2010). "Both HDAC1 and HDAC2 play important roles in the aggressiveness and carcinogenesis of gastric cancer." (PMID 21080974, 2010). "Network analysis methods have shown that statins, which are drugs against dyslipidemia, and lovastatin in particular, are beneficial for patients with gastric cancer due to the inhibition of histone deacetylase 2 (HDAC2), overexpression of which characterizes gastric tumors’ cells." (PMID 41283338, 2025). "The overexpression of HDA1 and HDAC2 is closely related to gastric cancer progression." (PMID 38920983, 2024). "HDAC2 was overexpressed in gastric cancer (GC) cell lines to utilize panobinostat for GC treatment." (PMID 37488424, 2023). "The availability of VPA in patients with gastric cancer may depend on patient selection based on biological parameters, such as HDAC2 overexpression." (PMID 21080974, 2010). "Moreover, HDAC1 and HDAC2 have been reported to be up-regulated in gastric cancer." (PMID 26036259, 2015). "In gastric cancer patients, HDAC2 expression was associated with negative lymph node metastasis." (PMID 21342584, 2011). "It is down-regulated in gastric cancer and exerts an inhibitory effect by binding to the 3′-UTR of HDAC2." (PMID 41002382, 2025). "There have been reported that histone deacetylase 2 was increased in human gastric cancer, and histone deacetylase 3 can inhibit the expression of DTWD1, which is a cancer suppressor gene in gastric cancer." (PMID 35463631, 2022). "HDAC1 and HDAC2 expression were evaluated by western blotting in OCUM-2MD3 cells and other gastric cancer cell lines (TMK-1, MKN-28)." (PMID 21080974, 2010).
ovarian carcinoma (27 papers, 2012 to 2024). A malignant neoplasm originating from the surface ovarian epithelium. "Given the involvement of the catalytic site, the sensitivity of HDAC2 to SAHA was evaluated in preclinical models of ARID1A-mutated ovarian cancers." (PMID 38794190, 2024). "Among them, HDAC1 and HDAC2 are class I HDACs, whose increased expression is an independent risk factor for poor prognosis of malignant ovarian tumors." (PMID 36172179, 2022). "Although these studies indicated that the increasing expression of HDAC2 was associated with tumor progression, our study is the first to demonstrate a clear correlation between HDAC2 expression and advanced stage ovarian cancer." (PMID 23420051, 2013). "As HDAC2 was reported to be highly expressed in ovarian cancer and associated with poor prognosis, we speculated that a regulatory relation may exist between HDAC2 and USP43." (PMID 38087046, 2024). "Together, elevated HDAC2 expression is associated with poor outcomes in ovarian cancer." (PMID 38794190, 2024). "The expression level of HDAC2 increases with the malignant degree of ovarian cancer, and high expression of HDAC2 is related to the poor prognosis of patients." (PMID 38087046, 2024). "Some studies have shown that USP5 promotes the proliferation of EOC cells by HDAC2 deubiquitylation, and silencing HDAC2 increases the sensitivity of ovarian cancer cells to cisplatin." (PMID 38087046, 2024). "HDAC2 plays a carcinogenic role in ovarian cancer, lung cancer, colorectal cancer and other cancers." (PMID 38087046, 2024). "In the early stage of platinum chemotherapy in ovarian cancer, cellular DNA damage increases HDAC2 expression, which induces chromatin remodeling and reduces the inhibitory effect of platinum on tumor cells." (PMID 36505774, 2022). "Inhibition of HDAC2 in a chemosensitive ovarian cancer cell line, PEO1, increased the efficacy of carboplatin treatment and increased γH2AX foci, and caused downregulation of phosphorylated BRCA1." (PMID 33669182, 2021). "Recently, ovarian cancer cells carrying ARID1A mutation showed higher sensitivity to SAHA and ACY1215 treatment, through inhibition of HDAC2 and HDAC6 activity respectively." (PMID 31165775, 2019). "In conclusion, class I HDACs HDAC1 and HDAC2 were highly expressed throughout all ovarian cancer cell lines whereas the other HDAC isoforms are expressed at a much lower level and only in some but not all cell lines." (PMID 31234549, 2019). "Western blotting analysis showed that the most affected Class I HDAC member in ovarian cancer cells with USP5 knockdown was HDAC2." (PMID 31727867, 2019). "We talked about the association between endometriosis and ovarian cancer, such as HDAC gene expression and the increase of proteins of both HDAC1 and HDAC2 in endometriosis and ovarian cancer." (PMID 29780815, 2018). "HDAC2 was upregulated after 24h of cisplatin treatment in vitro, with similar results seen in vivo in ovarian cancer xenografts." (PMID 26683361, 2016). "Studies in vivo using a patient-derived ovarian cancer xenograft model also showed elevated HDAC2 and HP1 isoform expression after chemotherapy." (PMID 26683361, 2016). "A notable aspect of our results is that the level of DNMT3b was correlated with HDAC1 and HDAC2 in ovarian cancer, which demonstrated that the two epigenetic events cooperated in controlling ovarian cancer progression." (PMID 23420051, 2013). "The relative expressions of HDAC 1, 2, 3 and 8 mRNA in ovarian cancers (n=22) were significantly higher than those in normal tissues (n=8), particularly for HDAC2 (P<0.01)." (PMID 23420051, 2013). "For example, expression of HDAC1 mRNA in human urinary bladder cancer specimens was significantly higher than that in normal controls, and increased mRNA expression of HDCA1 and HDAC2 was detected in ovarian cancer tissues compared with normal tissue samples." (PMID 23110995, 2012).
ovarian carcinoma (continued). "Regarding increasing of ESRα /β ratio as well as overexpression of HDAC2 that have been reported in several tumor cells, such as ovarian cancer, our data make us more cautious in the long-lasting exposure to the high concentrations of complex phytoestrogens in the combination of these two plants." (PMID 36788561, 2023). "HDAC2 knockdown partially abrogated USP5-promoted ovarian cancer cell proliferation." (PMID 31727867, 2019). "Considering the association between USP5 and HDAC2, we hypothesized that USP5 amplification may affect the sensitivity of ovarian cancer cells to HDAC inhibitor." (PMID 31727867, 2019). "This has also been demonstrated in PE01 (cisplatin-sensitive) and PE04 (cisplatin-resistant) ovarian cancer cells soon after cisplatin treatment (24 h), the authors suggesting changes in nuclear texture by HDAC2 are possibly a mediator of an early DNA damage response in sensitive tumour cells." (PMID 29899862, 2018). "Furthermore, the expression of DNMT1, DNMT3b, HDAC1 and HDAC2 was significantly higher in stage III/IV compared with stage I/II ovarian carcinomas." (PMID 23420051, 2013). "Thus, we speculate that USP5 may be a deubiquitinase of HDAC2, which negatively regulated the expression of p27 and p21 and led to the accelerated cell cycle transition and cell proliferation in ovarian cancer cells." (PMID 31727867, 2019). "Furthermore, HDAC1, HDAC2 and DNMT3b cooperated in controlling ovarian cancer progression and the HDACs may upregulate the expression of DNMTs." (PMID 23420051, 2013). "The mRNA expression of DNMT1, DNMT3b, HDAC1 and HDAC2 were particularly prominent in high-grade tumors in ovarian cancers, which indicated that they may be the biomarkers of tumor aggressiveness and proliferation, as their high expression is closely associated with ovarian carcinoma progression." (PMID 23420051, 2013). "In addition, HDAC1, HDAC2 and DNMT3b cooperated in controlling ovarian cancer progression." (PMID 23420051, 2013). "In ovarian cancer cells, the expression of HDAC1 and HDAC2 was significantly positively correlated with the expression of Ki-67, which is essential for the proliferation of ovarian cancer cells." (PMID 37894746, 2023). "In ovarian cancer, HDAC1 promotes cancer cell proliferation by increasing cyclin A, and HDAC2 interferes with cisplatin-induced activation of DNA damage responses by remodeling chromatin." (PMID 36172179, 2022). "Similar to ovarian carcinomas, high-grade endometrial carcinomas express high levels of HDAC1, HDAC2 and HDAC3, while less aggressive subtypes show lower levels of HDAC expression." (PMID 33669182, 2021). "USP5 overexpression increased the sensitivity of ovarian cancer cells to HDAC inhibitor PXD101, which was reversed by HDAC2 knockdown." (PMID 31727867, 2019).
melanoma (26 papers, 2016 to 2025). A malignant, usually aggressive tumor composed of atypical, neoplastic melanocytes. "This indicates that inhibiting the HDAC2 activity, which maybe one of the underlying mechanisms for drug-resistance in melanoma cells, is potentially helpful in controlling drug-resistant cancer." (PMID 30909413, 2019). "As a result, GTPs suppressed melanoma progression by regulating the circ_MITF/miR-30e-3p/HDAC2 axis, revealing a potential therapeutic strategy for the human malignant melanoma intervention." (PMID 36829966, 2023). "Another study presented GTPs suppressed melanoma via regulating the circ_MITF/miR-30e-3p/HDAC2 axis." (PMID 37764768, 2023). "This epigenetic factor is highly involved in primary melanoma formation and cooperates with histone deacetylase 2 (HDAC2) to favor a more proliferative state by epigenetically repressing genes of the invasive signature." (PMID 36551603, 2022). "In almost all investigated melanoma cell lines, high basal HDAC2 expression seemed to be correlated with lower basal BRN3A expression and vice versa." (PMID 35055045, 2022). "ChIP-Seq experiments after HDAC2 inhibition were performed using the melanoma cell line WM9 with low basal BRN3A gene expression levels instead of melanocytes, due to technical issues (sufficient cell number, high grade of pigmentation)." (PMID 35055045, 2022). "Intriguingly, SALL4 appears to regulate a melanoma-specific invasion program through HDAC2-mediated epigenetic silencing of invasiveness genes." (PMID 34417458, 2021). "Increased expression of HDAC2 is seen in human melanoma cells (Malme3MR) that have been made resistant to various anti-cancer drugs by repeated exposure to the anti-cancer drug celastrol." (PMID 32626712, 2020). "The survival time of HDAC2-MUT mice was longer than that of HDAC2-WT mice, indicating that the HDAC2 mutation partially reversed the promotion of NOS1 on lung metastasis of melanoma." (PMID 31805977, 2019). "Consistent with previous reports, our results also showed that the expression and activity of HDAC2 were positively correlated with ISG transcription in melanoma cells." (PMID 31805977, 2019). "In this study, we show evidence of H4K16 deacetylation by HDAC2 under IFNα stimulation conditions in melanoma cells, providing a molecular mechanism of HDAC2 involvement in the regulation of ISG expression through histone modification." (PMID 31805977, 2019). "Expression levels of HDAC1 and HDAC2 are higher in melanoma cells resistant to anti-cancer drugs than those in melanoma cells sensitive to anti-cancer drugs." (PMID 30583572, 2018). "In melanoma cells knock down of [HDAC6 + HDAC2] or [HDAC6 + HDAC10] significantly enhanced pazopanib lethality whereas knock down of [HDAC6 + HDAC1] or [HDAC6 + HDAC3] were less effective." (PMID 29137331, 2017). "Our previous GSEA of melanoma cell lines revealed that NTN4 was down-regulated in osteosarcoma cells following knockdown of HDAC2, suggesting that it is epigenetically regulated in cancer cells." (PMID 27172792, 2016). "The binding of VPA to HDAC2 enhanced the sensitivity of melanoma cells to radiation." (PMID 36968022, 2023). "Strikingly, ChIP-Seq analysis using the melanoma cell line WM 9 revealed that HDAC2 inhibition leads to an enrichment of H3K27ac at one specific promoter/enhancer element that is located 55.4 kb upstream of the BRN3A TSS within the proximal promoter of the RNF219 gene." (PMID 35055045, 2022). "Since CAGE could bind to HDAC2 in anti-cancer drug-resistant melanoma cells, it will be interesting to examine whether CAGE could bind to PELP1." (PMID 35682560, 2022). "Thus, SALL4 appears to regulate phenotype switching in melanoma through an HDAC2-mediated mechanism." (PMID 34417458, 2021).
melanoma (continued). "This further strengthens the hypothesis that SALL4 and HDAC2 together regulate melanocyte and melanoma-specific cellular processes." (PMID 34417458, 2021). "Lack of H4K16 deacetylation by HDAC2 nitrosylation leads to the loss of ISGs expression in melanoma cells." (PMID 34947954, 2021). "The binding of VPA to HDAC2 reverses the drug resistance in melanoma and induces the cell death." (PMID 30909413, 2019). "Interestingly, in animal models, lung metastasis was significantly reduced after knockout of HDAC2 in melanoma cells, suggesting that HDAC2 is a tumor-promoting factor, and other studies also support this finding." (PMID 31805977, 2019). "CAGE binds to HDAC2 and confers resistance to anti-cancer drugs in melanoma cells." (PMID 30619741, 2018). "Furthermore, reduced PIPP copy number has been reported in 15–20% of primary melanomas and melanoma cell lines, and PIPP expression is epigenetically suppressed by HDAC2 and -3-mediated histone hypoacetylation in melanoma cell lines." (PMID 28082369, 2017). "NOS1 reduces the recruitment of STAT1-mediated HDAC2 to ISG promoters and promotes lung metastasis of melanoma through the S-nitrosylation of HDAC4-C16/C229." (PMID 38877096, 2024). "In melanoma, PD-L1 seems to be directly controlled primarily by class I HDACs (HDAC1, HDAC2, HDAC3, HDAC8)." (PMID 38672128, 2024). "Consistent with previous findings, FK228, a potent HDAC1 and HDAC2 inhibitor, significantly reduced the HIF-1α protein levels in melanoma." (PMID 36831463, 2023). "Altogether, our data suggest that HDAC2 is a key epigenetic regulator of BRN3A in melanocytes and melanoma cells." (PMID 35055045, 2022). "In melanoma cells, NOS1-dependent impairment of interferon-α response relies on Cys272 and Cys274 HDAC2 nitrosylation." (PMID 34947954, 2021). "This study provides evidence that NOS1 induces dysfunctional IFN signaling to promote lung metastasis in melanoma, highlighting NOS1-induced S-nitrosylation of HDAC2 in the regulation of IFN signaling via histone modification." (PMID 31805977, 2019). "Our findings suggest that HDAC2 is not the sole regulator of BRN3A and that additional specific interaction partners or transcriptional regulators are likely to be involved in the recruitment of HDAC2 to the BRN3A gene locus and its aberrant expression in melanoma." (PMID 35055045, 2022). "We detected moderate to high global HDAC2 expression levels in a panel of melanoma cells and no expression or only relatively low levels in melanocytes." (PMID 35055045, 2022). "Here we show that SALL4 can build a protein complex together with HDAC2 also in human melanoma cells and that SALL4 and HDAC2 together directly bind to genes involved in melanocyte and melanoma biology, such as VEGFR-1, CDH2 (N-cadherin), FN1, TGFBR2, MITF, and others." (PMID 34417458, 2021). "This phenomenon is important for lung metastasization of melanoma, as mice injected with melanoma cells carrying non-nitrosylable form of HDAC2 (C272A/C274A) do not develop lung metastases." (PMID 34947954, 2021). "Thus, our study demonstrated a linkage between the S-nitrosylation of HDAC2 and the regulation of ISG expression, providing an endogenous NO-mediated mechanism for the dysfunction of the IFNα response in melanoma cells." (PMID 31805977, 2019). "For example, inhibition of the class I HDAC1, HDAC2 and/or HDAC3 led to acetylation of the PD-L1 and PD-L2 promotors, which augmented up-regulation of PD-L1/L2 protein and RNA transcription in melanoma patients, in melanoma cell lines and in a syngeneic mouse model of melanoma." (PMID 29843754, 2018).
melanoma (continued). "In previous experiments, we could not rule out the effect of endogenous HDAC2 on lung metastasis; therefore, we further constructed a mouse melanoma (B16F10-NOS1) cell line that knocked out HDAC2 using the CRISPR/Cas9 gene editing method." (PMID 31805977, 2019). "Moreover, expression of a mutant form of HDAC2, which cannot be nitrosylated, reverses the inhibition of ISG expression by NOS1 in vitro and decreases NOS1-induced lung metastasis and inhibition of tumor infiltrating lymphocytes in a melanoma mouse model." (PMID 31805977, 2019). "Thus, HDAC2 but not HDAC1 seems to be the critical HDAC that influences the BRN3A expression in melanocytes and melanoma cells with low endogenous mRNA expression of BRN3A." (PMID 35055045, 2022).